NLRC5 (NLR family CARD domain containing 5)
Diseases named in the same sentence as NLRC5 in open-access papers (continued):
Sharing a sentence is not in itself a finding about the gene and the disease.
keloid (4 papers, 2018 to 2024). An irregularly shaped, elevated mark on the skin caused by deposits of excessive amounts of collagen during wound healing. "NLRC5 is also highly expressed in keloids, fibrotic tumours in the skin that arise due to fibroblast hyperproliferation and increased expression of the extracellular matrix." (PMID 33925158, 2021). "Knockdown of NLRC5 inhibits production of extracellular matrix components in keloid fibroblasts." (PMID 33925158, 2021).
non-small cell lung carcinoma (4 papers, 2019 to 2024). A group of at least three distinct histological types of lung cancer, including non-small cell squamous cell carcinoma, adenocarcinoma, and large cell carcinoma. "In non-small cell lung cancer, NLRC5 promotes tumor progression by activating the PI3K/AKT pathway, thereby leading to carboplatin resistance." (PMID 38822039, 2024).
type 2 diabetes (4 papers, 2015 to 2026). "Specifically, IRF7 and NLRC5 are associated with type 2 diabetes, and SP110 and ZBP1 are associated with waist circumference and body fat distribution, respectively." (PMID 25868721, 2015).
chronic periodontitis (3 papers, 2017 to 2022). A chronic inflammatory process that affects the tissues that surround and support the teeth. "In chronic periodontitis, the rs289723 in NLRC5 gene was associated with chronic slight and chronic localized periodontitis susceptibility and the AA genotype was correlated with increased risk of disease development." (PMID 35407478, 2022).
diabetic nephropathy (3 papers, 2018 to 2024). "NLRC5 has been proposed for targeted therapy related to immune system regulation in central nervous disorders and diabetic nephropathy." (PMID 38571307, 2024). "As the largest NLR, NLRC5 participated in the pathogenesis of renal fibrosis, ischemia–reperfusion renal injury and diabetic nephropathy via modulating various signaling pathways including NF-κB and TGF-β/Smad." (PMID 31186034, 2019). "Besides NOD2 and NLRP3, NOD-like receptor family CARD domain containing 5 (NLRC5), the largest NLR, also participates in the developments of many kidney diseases including ischemia–reperfusion injury and diabetic nephropathy in various manners." (PMID 31186034, 2019).
Hepatic steatosis (3 papers, 2018 to 2021). Steatosis is a term used to denote lipid accumulation within hepatocytes. "The MEG3/miR-let-7c-5p/NLRC5 axis functions as an important player in EtOH-induced hepatic steatosis and apoptosis." (PMID 29692724, 2018). "Taken together, our data indicate that the MEG3/miR-let-7c-5p/NLRC5 axis functions as an important player in EtOH-induced hepatic steatosis and apoptosis." (PMID 29692724, 2018). "Functional studies have suggested that NLRC5 could positively regulate ethanol-induced hepatic steatosis." (PMID 31824312, 2019). "Previous studies from our laboratory have proved that NLRC5 plays a negative role in ethanol-induced hepatic steatosis." (PMID 29692724, 2018).
lymphoma (3 papers, 2020 to 2023). A malignant (clonal) proliferation of B- lymphocytes or T- lymphocytes which involves the lymph nodes, bone marrow and/or extranodal sites. "Similarly, NLRC5-FL and NLRC5-SA caused only a small increase in MHC-I expression in EL4 lymphoma cells, yet EL4-NLRC5-FL and EL4-NLRC5-SA cells formed significantly smaller tumors than EL4-vector control cells." (PMID 37108368, 2023). "Although further investigation across subtypes is required to definitively establish if somatic NLRC5 mutations are limited to aggressive lymphomas, the lack of somatic mutations in FL that we observed suggests this is not a major mechanism of MHC‐I‐mediated immune evasion in indolent lymphoma." (PMID 35845006, 2020).
renal fibrosis (3 papers, 2019 to 2026). A final common manifestation of a wide variety of chronic kidney diseases characterized by glomerulosclerosis and tubulointerstitial fibrosis. "Knockout of NLRC5 dramatically could inhibit the proliferation of renal fibrosis cells and decrease the accumulation of ECM." (PMID 31824312, 2019).
steatosis (3 papers, 2018 to 2025). Increased lipid within the cytoplasm of cells. "In contrary to MEG3, miR-let-7c-5p overexpression attenuated EtOH-induced steatosis and apoptosis, as well as suppressed EtOH-induced increase in NLRC5 expression." (PMID 29692724, 2018). "lncRNA MEG3, as a competing endogenous RNA (ceRNA) for miR-let-7c-5p, inhibited the interaction of miR-let-7c-5p with the binding of NLRC5’s 3' untranslated region (3'UTR), which promoted NLRC5 expression and further aggravated alcohol-induced steatosis and apoptosis." (PMID 40130250, 2025).
acute kidney injury (2 papers, 2020 to 2021). Sudden and sustained deterioration of the kidney function characterized by decreased glomerular filtration rate, increased serum creatinine or oliguria. "Previous studies have shown that NLRC5 can mediate apoptosis in acute kidney injury, cerebral ischemia/reperfusion injury, and acute myocardial infarction." (PMID 34095138, 2021).
breast tumors (2 papers, 2020 to 2024). "In human breast tumors, the loss of NLRC5 expression is highly infrequent, whereas around half of cases show complete loss of MHC-I expression." (PMID 32545680, 2020). "Taken together, these data suggest that in the LUAD, LUSC and breast tumors, changes in the expression of NLRC5, CIITA, IFNG as well as hypermethylation may play a role in the repression of HLA." (PMID 39358601, 2024).
COVID-19 (2 papers, 2022 to 2024). A disease caused by infection with severe acute respiratory syndrome coronavirus 2. "Moreover, also NLRC5 expression may be dysregulated by other mechanisms such as promoter methylation, copy number alterations and genetic mutations and, as suggested, its expression levels may be associated with COVID-19 severity and mortality." (PMID 36325330, 2022). "Interestingly, we found that COVID-19 patients displayed altered methylation in NLRC5." (PMID 36325330, 2022). "The increased expression of selected IFN-I (OAS1, OAS2, and IFIT1) and inflammasome related genes (CASP1, CASP5, NLRC5 and NAIP) between COVID-19 and HC PMNs was confirmed by RT-qPCR." (PMID 39172744, 2024). "OAS1 gene, an interferon stimulated gene (ISG), showed significant upregulation by IFN-I in COVID-19 PMNs as compared to HC PMNs, while the inflammasome related genes IL-1β, CASP1 and NLRC5 were more efficiently induced in HC PMNs than COVID-19 PMNs." (PMID 39172744, 2024).
depression (2 papers, 2023 to 2025). "Therefore, LPS was intraperitoneally injected into WT or Nlrc5 knockout (Nlrc5−/−) mice for five consecutive days to establish a mouse depression model, and some behavioral experiments, including OFT, SPT, TST, and FST, were performed." (PMID 37686068, 2023). "Nlrc5 knockout also decreased the number of microglia in the LPS-induced depression model." (PMID 37686068, 2023). "Considering that the abnormal activation of microglia was shown to be an important factor in mood disorders, further exploration was conducted to identify whether NLRC5-related microglia activation played a critical role in depression." (PMID 37686068, 2023). "Therefore, further studies are required to delve into the function of NLRC5 in neurons and microglia in the etiology of depression." (PMID 37686068, 2023). "A knockout of NLRC5 in neurons might also contribute to the pathophysiology of depression." (PMID 37686068, 2023). "Therefore, targeting NLRC5 might be promising for the future treatment of patients with depression." (PMID 37686068, 2023). "Nonetheless, the exact roles of NLRC5 in microglial activation and its function in depression have not been investigated yet." (PMID 37686068, 2023). "Although a transcriptomic study of patients with psychiatric disorders reveals that NLRC5 is highly expressed in brain tissue, the exact function of NLRC5 in the regulation of microglia in the pathology of depression has not been investigated." (PMID 37686068, 2023).
diffuse large B-cell lymphoma (2 papers, 2020 to 2022). "In diffuse large B cell lymphoma (DLBCL) with EZH2Y641 mutation, treatment with an EZH2 inhibitor reduced H3K27me3 in the promoter region of NLRC5, resulting in increased NLRC5 and MHC-I expression." (PMID 35343573, 2022).
glioblastoma (2 papers, 2024 to 2025). The most malignant astrocytic tumor (WHO grade IV). "One possible explanation is that CD163 scavenges hemoglobin-haptoglobin complexes, lowering heme levels, thereby possibly reducing NLRC5 expression, contributing to T cell exhaustion in glioblastoma." (PMID 39349952, 2024). "Selective antigenic silencing is most evident in glioblastoma (GBM) hypermethylation or Polycomb occupancy at CIITA, NLRC5, TAP1/2, and HLA-A/B loci downregulates MHC-I/II expression without altering other immune programs." (PMID 41341594, 2025). "Although it is not yet possible to induce NLRC5 expression pharmacologically, its activation could offer a promising therapeutic strategy to enhance immunity against glioblastoma and other cancers." (PMID 39349952, 2024).
lupus nephritis (2 papers, 2018 to 2019). Glomerulonephritis in the context of systemic lupus erythematosus. "However, we found that the phenomenon of NLRC5 in IgAN is similar to C3 complement in kidney diseases such as lupus nephritis, in which it was reported that C3 is associated with the activity and deterioration of lupus nephritis." (PMID 30453994, 2018). "IgAN appears to be a systemic disease, with the kidney is an important target organ for immune complex deposits, and we found NLRC5 in IgAN like C1q complement in lupus nephritis." (PMID 30453994, 2018). "The expression of NOD2, NLRP3 and NLRC5 was significantly higher in kidneys from AAV patients than those from normal controls, minimal change disease or class IV lupus nephritis." (PMID 31186034, 2019).
neuroblastoma (2 papers, 2021 to 2023). Neuroblastoma (NB) is the most common solid, extracranial childhood tumor. "In the murine neuroblastoma cell line, Neuro2a, NLRC5-induced MHC I activation requires the recruitment of NLRC5 to other transcriptional factors that bind to W/S-X-Y promoter domains." (PMID 34658795, 2021).
osteoarthritis (2 papers, 2021 to 2024). A noninflammatory degenerative joint disease occurring chiefly in older persons, characterized by degeneration of the articular cartilage, hypertrophy of bone at the margins and changes in the synovial membrane. "However, the role of NLRC5 in osteoarthritis (OA) has not been reported." (PMID 34438368, 2021).
ovarian carcinoma (2 papers, 2023). A malignant neoplasm originating from the surface ovarian epithelium. "The correlation between PD-L1 and NLRC5 expression in ovarian cancer was evaluated using the Cancer Genome Atlas database." (PMID 37113720, 2023). "We demonstrated that PD-L1 and NLRC5 expressions are positively correlated in ovarian cancer and that they co-vary in tandem in response to heat stress." (PMID 37113720, 2023). "Impaired function and expression of NLRC5 have been reported in many cancer types, among which ovarian cancer carries the highest frequency of copy number alterations of the NLRC5 gene." (PMID 37113720, 2023). "Results indicated a significant positive correlation between NLRC5 and PD-L1 in ovarian cancer." (PMID 37113720, 2023). "Therefore, it is particularly compelling to realise how HT affects these two significant targets of cancer immune evasion mechanisms (PD-L1 and NLRC5) when considering the integration of HT into immunotherapy strategies for treating ovarian cancer." (PMID 37113720, 2023). "Therefore, recovering MHC class 1 genes via NLRC5 targeting may represent a promising strategy to increase the efficacy of PD-1/PD-L1 inhibitors in ovarian cancer." (PMID 37113720, 2023). "In this context, we sought to investigate the effect of HT on PD-L1 and NOD-like receptor family CARD domain containing 5 (NLRC5) identified as the key transcriptional activator of MHC-1 genes, and their interaction in ovarian cancer." (PMID 37113720, 2023). "PD-L1 and NLRC5 are positively correlated (Pearson’s r = 0.54, p-value < 0.001) in ovarian cancer but not in normal tissue." (PMID 37113720, 2023). "Moreover, the positive correlation between PD-L1 and NLRC5 led us to conclude that the upregulation of PD-L1 and the downregulation of MHC class I are two mutually exclusive mechanisms of immune evasion in ovarian cancer." (PMID 37113720, 2023).
pancreatic cancer (2 papers, 2020 to 2021). "In our murine pancreatic cancer cell lines, we found that the parental cell line Panc02 had much higher expression of NLRC5 than the Panc02SIY100 subclone, correlating with its much higher basal expression of MHC-I." (PMID 32355214, 2020).
Parkinson disease (2 papers, 2023). A progressive degenerative disorder of the central nervous system characterized by loss of dopamine producing neurons in the substantia nigra and the presence of Lewy bodies in the substantia nigra and locus coeruleus. "As reported in a recent study, NLRC5 promotes MPP+/LPS-induced microglial and astrocyte activation in Parkinson’s Disease (PD) models." (PMID 37686068, 2023).
rectal cancer (2 papers, 2018 to 2022). A primary or metastatic malignant neoplasm that affects the rectum. "Some other studies reported that there was also an association between NLRC5 SNPs and the survival of colorectal and rectal cancer." (PMID 35407478, 2022). "Logistic regression analysis adjusted for age and gender reported a moderate association between rectal cancer risk and two NLRC5 SNPs, rs1684575 T>G (OR: 1.60, 95% CI: 1.13–2.27, recessive model) and rs3751710 (OR: 0.70, 95% CI: 0.51–0.96, dominant model)." (PMID 29408916, 2018). "Logistic regression analysis adjusted for age and sex reported an association between rectal cancer risk and 2 NLRC5 SNPs, rs1684575 (OR: 1.60, 95% CI: 1.13–2.27, recessive model) and rs3751710 (OR: 0.70, 95% CI: 0.51–0.96, dominant model)." (PMID 29408916, 2018).
Rota virus infection (2 papers, 2021). "NLR Family CARD Domain Containing 5 (NLRC5) had a weak moderate effect for modulating CD8 + T-cell responses in mice small intestine with rotavirus infection." (PMID 34025929, 2021).
spleen diseases (2 papers, 2019 to 2024). "Indeed, our understanding of NLRC5′ role in lung and spleen diseases is extremely poor and remains to be improved." (PMID 31824312, 2019).
type 1 diabetes (2 papers, 2016 to 2023). "In order to understand the factors that might drive islet HLA-I hyperexpression in type 1 diabetes, we studied NLRC5, a known transcriptional regulator of HLA-ABC and β2M." (PMID 27506584, 2016). "Expression of NLRC5 was similarly detected in the islets of patients with type 1 diabetes but was not elevated, even in islets with demonstrably elevated HLA-ABC expression." (PMID 27506584, 2016).
bipolar disorder (1 paper, 2022). A disorder of the brain that causes unusual shifts in mood, energy, activity levels and the ability to carry out day-to-day tasks. "A transcriptomic analysis of the dorsal striatum comparing individuals with bipolar disorder and controls found significant changes in the expression of 14 genes, including a few immune response genes, such as NLRC5, S100A12, LILRA4, and FCGB27." (PMID 36371440, 2022).
brain cancer (1 paper, 2021). A primary or metastatic malignant neoplasm affecting the brain. "In fact, liver, colon and brain cancer tissues show elevated NLRC5 expression, which is thought to result from high inflammatory conditions." (PMID 33671123, 2021). "In this context, it is noteworthy that the Kobayashi group has observed elevated NLRC5 mRNA expression in liver, colon and brain cancer tissues within the TCGA study cohorts." (PMID 33671123, 2021).
cardiac hypertrophy (1 paper, 2024). "NLRC5 overexpression improves cardiac hypertrophy by inactivating the mTOR pathway, thereby increasing autophagy." (PMID 39519229, 2024).
celiac disease (1 paper, 2019). An autoimmune genetic disorder with an unknown pattern of inheritance that primarily affects the digestive tract. "On the other hand, the top non-HLA DMRs in celiac disease mapped to genes related to the immune response, including NLRC5 and TMEM105 in the epithelial fraction, and CAST and HOXC4 in the immune compartment." (PMID 30718669, 2019).
chronic lung infection (1 paper, 2025). "Furthermore, we established chronic lung infection models in wild-type and Nlrc5 knockout mice." (PMID 41170846, 2025).
colon adenocarcinoma (1 paper, 2018). "NLRC5 was expressed to varying degrees in healthy gut tissue and most highly in colon adenocarcinoma, and was inducible by IFNγ in HCT116 cells." (PMID 29928061, 2018).
cytomegalovirus infection (1 paper, 2018). A herpesvirus infection caused by Cytomegalovirus. "The authors show that siRNA-mediated silencing of NLRC5 impairs the upregulation of IFN-α after human cytomegalovirus infection of human foreskin fibroblasts." (PMID 30344524, 2018).
diabetic retinopathy (1 paper, 2021). "Nlrc5 deficiency is associated with neointimal hyperplasia, aortic smooth muscle proliferation, chronic inflammation and diabetic retinopathy; Therefore, its decrease is consistent with gut pathophysiology in hypertension." (PMID 34204247, 2021).
dyslipidemia (1 paper, 2023). "Moreover, NLRC5 was identified as a candidate gene to affect HDL-Clevels in humans and single nucleotide polymorphisms (SNP) in NLRC5, and its promotors have been associated with altered triglyceride levels and dyslipidemia." (PMID 37239938, 2023).
epilepsy (1 paper, 2021). A brain disorder characterized by episodes of abnormally increased neuronal discharge resulting in transient episodes of sensory or motor neurological dysfunction, or psychic dysfunction. "Theiler’s murine encephalomyelitis virus (TMEV) infection induces a well-characterized experimental model of epilepsy, resulting in increased expression of NLRC5 and MHC I (H2-Kb) mRNAs and significantly decreased expression of IFN-I and pro-inflammatory mediators in normal mouse brains." (PMID 34220868, 2021). "Thus, inhibiting the acute elevation of NLRC5 levels or its downstream signaling molecules, such as IL-1β, is a promising therapeutic strategy for epilepsy." (PMID 34220868, 2021).
hemophagocytic lymphohistiocytosis (1 paper, 2024). "In summary, the study highlights the disease relevance of NLRC5, showing its role in heme-mediated kidney damage as well as inflammation and mortality in hemolytic disease, hemophagocytic lymphohistiocytosis (HLH), and colitis." (PMID 39349952, 2024).
influenza (1 paper, 2020). An acute viral infection of the respiratory tract, occurring in isolated cases, in epidemics, or in pandemics; it is caused by serologically different strains of viruses (influenzaviruses) designated A, B, and C, has a 3-day incubation period, and usually lasts for 3 to 10 days. "NLRC5 interacts with RIG-I to induce a robust response to the influenza virus; overexpression of NLRC5 resulted in impaired influenza viral replication." (PMID 32508793, 2020).
ischemia (1 paper, 2021). A hypoperfusion of the BLOOD through an organ or tissue caused by a PATHOLOGIC CONSTRICTION or obstruction of its BLOOD VESSELS, or an absence of BLOOD CIRCULATION. "We further found that NLRC5 was upregulated in retinal microglia during ischemia, while NLRC5 knockdown significantly ameliorated retinal ischemic damage and RGC death." (PMID 34095138, 2021). "Through an in-depth analysis of our recently published transcriptome data, we found that NLRC5 was significantly up-regulated in retina during ischemia–reperfusion injury, which were further confirmed by subsequent detection of mRNA and protein level." (PMID 34095138, 2021). "We found that NLRC5 was also upregulated in retinal microglia during ischemia, suggesting that NLRC5 may exert its function though retinal microglia." (PMID 34095138, 2021).